AFMID (arylformamidase)
Description:
Catalyzes the hydrolysis of N-formyl-L-kynurenine to L-kynurenine, the second step in the kynurenine pathway of tryptophan degradation. Kynurenine may be further oxidized to nicotinic acid, NAD(H) and NADP(H). Required for elimination of toxic metabolites.
Synonyms: KFA; FKF; DKFZp686F03259; KF
Tractability: PROTAC: ubiquitination databases record sites on it.
Gene: Protein-coding gene on chromosome 17 (78,187,330 to 78,207,703, forward strand). Ensembl gene ENSG00000183077.
Subcellular location: Cytoplasm, cytosol; Nucleus
Subcellular location (Human Protein Atlas): Mitochondria
Pathways (Reactome):
Metabolism: Tryptophan catabolism
Gene Ontology:
Molecular function: protein binding; arylformamidase activity; hydrolase activity
Biological process: 'de novo' NAD+ biosynthetic process from L-tryptophan
Cellular component: cytoplasm; cytosol; nucleus
Genetic constraint (gnomAD): Loss-of-function variants: 39 observed, 50.04 expected, observed/expected ratio (o/e) 0.78, 90% interval 0.6 to 1.02. The upper end of that interval is the gene's LOEUF score, 1.02, which puts it in group 4 of 6, group 1 being the genes least tolerant of losing a copy. Missense variants: 375 observed, 398.83 expected, observed/expected ratio (o/e) 0.94, 90% interval 0.86 to 1.02. Synonymous variants: 130 observed, 156.97 expected, observed/expected ratio (o/e) 0.83, 90% interval 0.72 to 0.96.
Homologues: Orthologues: chimpanzee AFMID (99% identical), macaque AFMID (92% identical), pig AFMID (75% identical), dog AFMID (75% identical), mouse Afmid (70% identical), guinea pig AFMID (70% identical), rat Afmid (67% identical), zebrafish afmid (42% identical), tropical clawed frog afmid (36% identical), Caenorhabditis elegans afmd-1 (25% identical), Drosophila melanogaster KFase (24% identical). Paralogues in human: AADAC (20% identical), AADACL4 (19% identical), AADACL3 (18% identical), AADACL2 (18% identical), NCEH1 (17% identical).
Diseases named in the same sentence as AFMID in open-access papers:
AFMID is named in the same sentence as 6 diseases in open-access papers, as found by Europe PMC text mining. Sharing a sentence is not in itself a finding about the gene and the disease. The quoted sentences say what the papers report.
colon cancer (3 papers, 2019 to 2021). "We found that the enzymes IDO1 and TDO2 were elevated in ∼40% of the samples from colon cancer patients, and the enzyme AFMID, which is involved in the last step of the conversion of Trp into Kyn, was up-regulated in 80% of these samples of colon cancers." (PMID 31416966, 2019). "Elevated levels of the enzymes TDO2, IDO1, and AFMID combined with the Trp transporters SLC1A5 and SLC7A5 in colon cancer patients may lead to increased Trp and Kyn levels in colon cancer cells." (PMID 31416966, 2019). "In a recent study centered on colon cancer, the KYN levels in tumor cells were higher than in adjacent normal cells due to upregulation of the specific transporter SLC7A5 and the enzyme arylformamidase (AFMID), which is involved in the conversion of Trp into KYN." (PMID 34445444, 2021).
glomerulosclerosis (1 paper, 2019). A hardening of the kidney glomerulus caused by scarring of the blood vessels. "Interestingly, deleting of arylformamidase (Afmid) in mice leads to a glomerulosclerosis phenotype." (PMID 30760699, 2019).
AFMID also shares sentences with these, for which no sentence is quoted: tumor (3 papers); cancer (2); glioma (1); hepatocellular carcinoma (1).